PITPNM2 (phosphatidylinositol transfer protein membrane associated 2)
Description:
Membrane-associated phosphatidylinositol (PI) transfer protein that shuttles PI between intracellular membranes and thereby maintains plasma membrane phosphoinositide signaling competence. Upon production of phosphatidic acid (PA), mediates the transfer of phosphatidylinositol from the endoplasmic reticulum to the plasma membrane at endoplasmic reticulum-plasma membrane contact sites. This transfer sustains phospholipase C (PLC)-coupled receptor signaling and replenishing of plasma membrane phosphoinositides following receptor-induced hydrolysis. Promotes PIP2 replenishment following TCR stimulation; plays a critical role in T cell development by supporting calcium signaling in response to weak TCR stimulation during TCRbeta selection and positive selection of thymocytes, as well as maintaining peripheral T cell survival (By similarity).
Synonyms: NIR-3; NIR3; RDGBA2; RDGB2
Tractability: Antibody: UniProt places it where antibodies can reach, with high confidence. PROTAC: ubiquitination databases record sites on it; its protein half-life has been measured.
Gene: Protein-coding gene on chromosome 12 (122,983,480 to 123,151,142, reverse strand). Ensembl gene ENSG00000090975.
Subcellular location: Cell membrane; Endoplasmic reticulum membrane
Subcellular location (Human Protein Atlas): Vesicles
Pathways (Reactome):
Metabolism: Synthesis of PI
Gene Ontology:
Molecular function: calcium ion binding; lipid transporter activity; phosphatidylinositol transfer activity; protein binding; receptor tyrosine kinase binding; phosphatidylcholine binding; phosphatidylcholine transporter activity; phosphatidylinositol binding; metal ion binding
Biological process: 1-phosphatidyl-1D-myo-inositol 4,5-bisphosphate biosynthetic process; positive regulation of 1-phosphatidyl-1D-myo-inositol 4,5-bisphosphate biosynthetic process; positive regulation of phospholipid transport; phosphatidylinositol biosynthetic process; intermembrane lipid transfer; lipid translocation; phospholipid transport
Cellular component: cytoplasmic side of plasma membrane; endoplasmic reticulum-plasma membrane contact site; cytoplasm; cytosol; endoplasmic reticulum membrane; plasma membrane
Genetic constraint (gnomAD): Loss-of-function variants: 35 observed, 129.07 expected, observed/expected ratio (o/e) 0.27, 90% interval 0.21 to 0.36. The upper end of that interval is the gene's LOEUF score, 0.36, which puts it in group 1 of 6, group 1 being the genes least tolerant of losing a copy. Missense variants: 1,325 observed, 1,832 expected, observed/expected ratio (o/e) 0.72, 90% interval 0.69 to 0.76. Synonymous variants: 737 observed, 761.41 expected, observed/expected ratio (o/e) 0.97, 90% interval 0.91 to 1.03.
Homologues: Orthologues: chimpanzee PITPNM2 (99% identical), macaque PITPNM2 (98% identical), rabbit PITPNM2 (92% identical), dog PITPNM2 (92% identical), guinea pig PITPNM2 (90% identical), rat Pitpnm2 (89% identical), pig PITPNM2 (88% identical), mouse Pitpnm2 (86% identical), tropical clawed frog pitpnm2 (76% identical), zebrafish pitpnm2 (55% identical). Paralogues in human: PITPNM1 (53% identical), PITPNM3 (42% identical), PITPNC1 (11% identical), PITPNB (9% identical), PITPNA (9% identical).
Diseases named in the same sentence as PITPNM2 in open-access papers:
PITPNM2 is named in the same sentence as 20 diseases in open-access papers, as found by Europe PMC text mining. Sharing a sentence is not in itself a finding about the gene and the disease. The quoted sentences say what the papers report.
allergic disease (2 papers, 2019 to 2022). An immune response that occurs following re-exposure to an innocuous antigen, and that requires the presence of existing antibodies against that antigen. "PITPNM2 was implicated as a risk locus of multiple sclerosis and allergic diseases which were all linked to RA." (PMID 31443559, 2019).
schizophrenia (2 papers, 2017 to 2022). A major psychotic disorder characterized by abnormalities in the perception or expression of reality. "A number of variants from the discovery set were not present in the replication sample, including a novel PITPNM2 missense variant, which is located in a highly significant schizophrenia GWAS locus." (PMID 28195573, 2017).
diverticular disease (1 paper, 2024). A complex disorder characterised by mucosal outpouchings (diverticulae) of the colonic wall which can become infected and inflamed leading to diverticulitis, perforation and bleeding. "Similarly, we found 24 GWS (Pgene-diverticular-disease < 2.62 × 10−6) genes for diverticular disease, two for IBS (Pgene-IBS < 2.62 × 10−6, HLA-C and PITPNM2), and 26 for IBD (Pgene-IBD < 2.62 × 10−6) that were associated with T2D (Pgene-T2D < 0.05)." (PMID 38802514, 2024).
duodenitis (1 paper, 2024). Acute or chronic inflammation of the duodenum. "Others included 41 GWS genes for GERD (Pgene-GERD < 2.62 × 10−6), 11 for PUD (Pgene-PUD < 2.62 × 10−6), three (RNF5, HLA-DQA1, and HLA-DQB1) for gastritis-duodenitis (Pgene-gastritis-duodenitis < 2.62 × 10−6), and three (HLA-C, PITPNM2, and MPHOSPH9) for IBS (Pgene-IBS < 2.62 × 10−6)." (PMID 38802514, 2024).
glioma (1 paper, 2025). A benign or malignant brain and spinal cord tumor that arises from glial cells (astrocytes, oligodendrocytes, ependymal cells). "SVs identified in the Mastiffs clade intersected with the introns of three genes: ABCB9, PITPNM2, and DENR, that last of which was found to have two intronic deletions and has been implicated in canine glioma susceptibility." (PMID 40971676, 2025).
virus infection (1 paper, 2022). "NKT cells of the peripheral blood in C. carbonaria were identified by PITPNM2, OGT, PRPF4B, PNISR, and CD3E genes, which had immunoregulatory roles in virus infection and cancer." (PMID 36552787, 2022).
PITPNM2 also shares sentences with these, for which no sentence is quoted: cancer (3 papers); asthma (2); multiple sclerosis (2); retinal degeneration (2); type 2 diabetes (2); autoimmune disease (1); bipolar disorder (1); breast carcinoma (1); depression (1); eczema (1); gastritis (1); glioblastoma (1); lymphopenia (1); mental disorder (1).